CRP (C-reactive protein)
Diseases named in the same sentence as CRP in open-access papers (continued):
Sharing a sentence is not in itself a finding about the gene and the disease.
acute pancreatitis (177 papers, 2004 to 2026). An acute inflammatory process that leads to necrosis of the pancreatic parenchyma. "This aligns with other published studies that identified CRP as a valuable biomarker for early risk stratification in acute pancreatitis." (PMID 39857010, 2025). "Previous publications have shown that it can predict the severity of acute pancreatitis, and pancreatic necrosis is strongly associated with a CRP level exceeding 150 mg/L within the initial 72 h period." (PMID 38279274, 2024). "If, at the beginning of the patient’s stay in the hospital or within the first 72 h, the CRP level is 14 286 nmol/L (150 mg/dL) or more, this suggests acute pancreatitis and is also associated with a worse clinical course." (PMID 36010324, 2022). "Some studies also shown weak association of CRP levels alone at admission and 48 h after hospital stay with complicated acute pancreatitis." (PMID 36268355, 2022). "Multiple persistent organ failure, age above 50, higher values of CRP, and surgery were risk factors for death in the patients with severe acute pancreatitis admitted to the intensive care unit of our hospital." (PMID 34829360, 2021). "Multiple persistent organ failure, age over 50, higher values of C reactive protein, and surgery were risk factors for death in the patients with severe acute pancreatitis admitted to the intensive care unit." (PMID 34829360, 2021). "One study did not favor the laboratory markers on admission had a prognostic value, rather NLR, PLR, and CRP/albumin ratio at 48 hours of hospital stay were significantly associated with acute pancreatitis complications." (PMID 34513375, 2021). "The MR-PheWAS identified the relationship between CRP and increased risk of bronchitis and acute pancreatitis." (PMID 34386016, 2021). "The aim of this study was to further elucidate the role of PTX3 as a diagnostic and prognostic marker in acute pancreatitis (AP), a potentially strong inflammatory disease, and compare it to CRP." (PMID 31798002, 2019). "Similarly, in dogs, elevated CRP/ALB ratios have been associated with increased mortality risk in acute pancreatitis." (PMID 40218453, 2025). "Likewise, some authors have documented that the use of LR has been linked to a significant decrease in C-reactive protein levels, a biomarker related to the severity of acute pancreatitis." (PMID 41002736, 2025). "High levels of NLR, PLR, RDW, glucose, CRP, urea, potassium, low albumin and hematocrit values at the first admission in the Emergency Department seem to be associated with increased 1-year mortality in acute pancreatitis." (PMID 33489590, 2020). "High levels of NLR, PLR, RDW, glucose, CRP, urea, potassium, low albumin and hematocrit values ​​at the first admission in the Emergency Service seem to be associated with increased 1-year mortality in acute pancreatitis." (PMID 33489590, 2020). "We confirmed that CRP and elastase analyzed on the third day of admission, in addition to the evaluation of IL-6, IL-8, IL-10, and sTNFr on the first day, represent a valuable diagnostic tool in the assessment of severity and course of disease in patients with acute pancreatitis." (PMID 23476635, 2013). "That means that PCT has greater prognostic value than CRP in predicting mortality among patients with acute pancreatitis, particularly after 48 h of hospitalization." (PMID 41515611, 2026). "The primary objective of this study was to compare changes in inflammatory markers, particularly C-reactive protein, between lactated Ringer's (LR) and normal saline (NS) in early acute pancreatitis." (PMID 42158793, 2026). "BACKGROUND: Acute pancreatitis triggers the production of acute-phase proteins (APPs) in the body, among which C-reactive protein (CRP) is the most extensively studied and widely used for both diagnosis and prognosis." (PMID 41807952, 2026).
acute pancreatitis (continued). "This study demonstrates that early proteolytic biomarker patterns, particularly urinary trypsin-2, are strongly associated with systemic inflammatory burden as reflected by CRP levels in acute pancreatitis." (PMID 41597402, 2026). "The other 4 (20%) were RTH for the following reasons: acute pancreatitis (n=1, 5%), acute pain crisis (n=1, 5%), a doubling of C-reactive protein (n=1, 5%), and neutropenic fever (n=1, 5%; the patient did not report VSM data)." (PMID 40418800, 2025). "In multivariate analysis, the model including the following independent predictors was associated with the severity of acute pancreatitis: CTSI score (p < 0.0001), BISAP score (p = 0.0082), and CRP levels at 48 h (p = 0.0091), respectively." (PMID 39857010, 2025). "The BISAP score, NLR, CRP, BISAP combined with NLR, and BISAP combined with CRP showed AUC values of 0.88, 0.81, 0.71, and 0.95, respectively, for predicting the severity of acute pancreatitis." (PMID 39857010, 2025). "Regarding the accuracy of predicting the severity of acute pancreatitis, CRP levels measured at 48 h emerged as a strong independent predictor of severe ABP, with an AUC of 0.92." (PMID 39857010, 2025). "CRP has been widely recognized as an inflammatory biomarker of clinical utility in monitoring the evolution of patients with acute pancreatitis." (PMID 41002736, 2025). "Analysis of the results obtained from the studies shows that CRP appears to be superior to LDH in staging melanoma, whereas their individual diagnostic powers differ in other conditions, such as acute pancreatitis." (PMID 40563651, 2025). "CRP emerges as a valuable marker for inflammation, capable of distinguishing between mild and severe acute pancreatitis." (PMID 39011189, 2024). "This indicates that the CRP/albumin ratio has a good discriminative ability to distinguish between mild and severe acute pancreatitis." (PMID 38283464, 2023). "A clinical trial found that C-reactive protein levels were lower in patients with acute pancreatitis following resuscitation with LRS than with normal saline." (PMID 37345662, 2023). "This study demonstrates the CRP/albumin ratio calculated within 24 hours of admission as a promising prognostic marker for predicting persistent organ failure in acute pancreatitis in the Indian population." (PMID 38283464, 2023). "This prospective observational study demonstrates that the CRP/albumin ratio, calculated within 24 hours of admission, can reliably predict persistent organ failure in acute pancreatitis." (PMID 38283464, 2023). "The present study aimed to evaluate the predictive utility of the C-reactive protein (CRP)/albumin (CRP/Alb) ratio in predicting outcomes of acute pancreatitis in Indian patients." (PMID 38283464, 2023). "For many specialists, CRP is considered as the predictive factor for severity of acute pancreatitis." (PMID 37724533, 2023). "It has been reported that the assessment of the severity of acute pancreatitis using indicators such as CRP has been shown to be useful in predicting AP." (PMID 37511976, 2023). "The CRP/Alb ratio calculated within 24 hours reliably predicts persistent organ dysfunction in Indian acute pancreatitis patients." (PMID 38283464, 2023). "CT scans and levels of C-reactive protein, hematocrit, and procalcitonin have also been used to predict the severity of acute pancreatitis, with varying degrees of success." (PMID 37378221, 2023). "Severe acute pancreatitis patients (n = 50) had higher CRP/Alb ratios than mild cases (0.45 vs. 0.20, p<0.001)." (PMID 38283464, 2023). "The CRP/albumin ratio demonstrated superior predictive performance for severe acute pancreatitis compared to the conventional Ranson scoring system in our study." (PMID 38283464, 2023). "On multivariate regression, CRP/Alb ratio >0.25 independently predicted severe acute pancreatitis after adjusting for age, gender, and CT severity index (adjusted OR 5.2, 95% CI 2.8-9.6)." (PMID 38283464, 2023).
acute pancreatitis (continued). "This shows the CRP/albumin ratio was significantly higher in severe AP; mild acute pancreatitis: 60 (40%); moderate acute pancreatitis: 16 (11%); severe acute pancreatitis: 74 (49%)." (PMID 38283464, 2023). "CRP > 150 mg/L is considered a gold standard 48 hours after acute pancreatitis onset, yet this was lower in the patient." (PMID 36911648, 2023). "•There is a need to diagnose the severity of acute pancreatitis using a single test ratio i.e., CRP/albumin ratio." (PMID 36268355, 2022). "For instance, CRP, an acute-phase reactant, has been shown repeatedly to predict severity of acute pancreatitis—although there has been debate about the optimal time point and cut-offs." (PMID 36057565, 2022). "Our systematic review has shown a positive correlation was found between the CRP/albumin ratio at admission and the development of subsequent severe acute pancreatitis, increased hospital length of stay, and higher rate of mortality in these studies." (PMID 36262941, 2022). "Treatment with genistein in both low and high doses effectively decreased levels of serum IL-6 and serum CRP suggesting the anti-inflammatory effect of genistein in acute pancreatitis." (PMID 35927726, 2022). "In our review, across these three studies, 956 patients with acute pancreatitis were identified and enrolled in studies that examined the relationship between the CRP/Albumin ratio and the severity of acute pancreatitis." (PMID 36262941, 2022). "A positive correlation was found between the CRP/albumin ratio at admission and the development of subsequent severe acute pancreatitis in these studies." (PMID 36262941, 2022). "Severely elevated CRP concentrations have been detected in many systemic disorders, such as pyometra, acute pancreatitis, polyarthritis, immune-mediated diseases like immune-mediated hemolytic anemia, and neoplastic diseases like hemangiosarcoma." (PMID 36713872, 2022). "In our review, across three studies, we identified 956 patients with acute pancreatitis that were enrolled in studies that examined the relationship of the CRP/albumin ratio with the severity of acute pancreatitis." (PMID 36262941, 2022). "A systematic review of the literature was performed using the keywords CRP albumin ratio and acute pancreatitis in the PubMed and Cochrane databases." (PMID 36262941, 2022). "The rationale of this study is to diagnose the severity of acute pancreatitis using a single test ratio, i.e., CRP/albumin ratio which is a combination of markers for systemic inflammation and nutritional status." (PMID 36268355, 2022). "It has been reported that CRP levels of more than 210 mg/L in acute pancreatitis differentiate mild and severe cases, with 83% sensitivity and 85% specificity." (PMID 36262941, 2022). "Overall, a positive correlation was found between the CRP/albumin ratio at admission and the development of subsequent severe acute pancreatitis, increased hospital length of stay, and the higher rate of mortality in these studies." (PMID 36262941, 2022). "High postoperative CRP levels can also be due to other conditions like acute pancreatitis or pulmonary embolism." (PMID 35306601, 2022). "Lastly, CRP/albumin ratio was considered a good prognostic marker in predicting severe acute pancreatitis with significantly moderate correlations with all severity scores and hospitalization period." (PMID 36268355, 2022). "CRP or high-sensitivity CRP has the greatest sensitivity to any type of inflammation, including anaphylactic shock and acute pancreatitis; however, its specificity is low for infection." (PMID 36555941, 2022). "CRP gradually increases with the severity of acute pancreatitis and generally peaks 36–72 h after the onset of symptoms; therefore, its measurement is not applicable to the determination of disease severity on admission." (PMID 36010324, 2022).
acute pancreatitis (continued). "Nevertheless, a decrease in 25(OH)D levels, accompanied by an increase in CRP, was also observed during the first days after acute pancreatitis and after the intravenous infusion of bisphosphonates." (PMID 35745092, 2022). "Early patient stratification according to the potential severity is of paramount importance in acute pancreatitis; hence, more studies are needed to assess the utility of the CRP/albumin ratio as a prognostic tool." (PMID 36262941, 2022). "Sixty-seven patients with acute pancreatitis (AP) who were hospitalized within 48 h of onset and received serum CRP and IL-6 tests from September 2018 to September 2019 were included." (PMID 36467730, 2022). "Recent studies demonstrated the elevation of IL-6 and CRP in animal models of caeruline and L-arginine induced acute pancreatitis." (PMID 35927726, 2022). "Even accounting for other inflammatory markers like Ferritin, CRP/albumin ratio stands out in predicting severity of the disease and mortality in acute pancreatitis." (PMID 36268355, 2022). "Recently, a meta-analysis carried out by van den Berg and colleagues showed a superiority of serum IL- 6 within the first 72 h for the early prediction of severity of acute pancreatitis, followed by increased serum CRP levels with adequate predictive values." (PMID 35566689, 2022). "While, one study conducted on animals determined role of CRP/albumin ratio in survival of acute pancreatitis." (PMID 36268355, 2022). "Based on this current situation, the value of neutrophil CD64 index, PCT, and CRP in predicting the incidence of acute pancreatitis complicated with abdominal infection was analyzed to provide evidence for clinical diagnosis of infectious diseases." (PMID 36292098, 2022). "Serum interleukin-6 (IL-6) and C-reactive protein (CRP) levels in patients with acute pancreatitis and their correlation with severity." (PMID 36467730, 2022). "By comparison CRP has been demonstrated to be elevated in canine acute pancreatitis, therefore, providing a potential avenue for differentiating acute pancreatitis from IVDH (perhaps more useful than cPLI )." (PMID 35751435, 2022). "The first criterion concerns the patients with acute pancreatitis diagnosed on the basis of CRP greater than 14,286 nmol/L (150 mg/L), an APACHE II score greater than 8, or organ dysfunction for more than 48 h despite sufficient fluid administration." (PMID 36010324, 2022). "Previous studies have shown CRP/albumin ratio as an important prognostic marker in acute pancreatitis." (PMID 36268355, 2022). "The CRP is generally thought to peak within 48 h after the onset of an infection or inflammatory disease, and therefore, patients with severe acute pancreatitis should be evaluated at the time of diagnosis and 48 h after onset." (PMID 34386599, 2021). "First, the maximum CRP level measured between the time of diagnosis of severe acute pancreatitis and day 7 postdiagnosis was identified as a statistically significant factor related to the onset of WON." (PMID 34386599, 2021). "The current review of 31 studies evaluating corticosteroid treatment of acute pancreatitis provides fair evidence indicating the beneficial effect of corticosteroids on the duration of hospitalisation and circulating CRP levels." (PMID 34256804, 2021). "CRP measured at admission or at 48 hours has a very limited role in the prediction of complicated acute pancreatitis." (PMID 34900460, 2021). "Our findings suggest the importance of continuous monitoring of CRP levels during the early stage of severe acute pancreatitis to predict the development of WON for a better outcome." (PMID 34386599, 2021). "Higher levels of YKL-40, chitotriosidase and C-reactive protein were found in patients with acute pancreatitis at onset than in remission." (PMID 34579512, 2021).
acute pancreatitis (continued). "Rao and Kunte measured serum IL-6, IL-8, IL-10, and C-reactive protein (CRP) levels within 24 h of admission in forty patients of clinically predicted severe acute pancreatitis (SAP)." (PMID 34349610, 2021). "Resistin is known to have a proinflammatory potential since serum resistin levels increase in parallel with C-reactive protein in acute pancreatitis." (PMID 34349610, 2021). "Taken together, these findings indicate that the close monitoring of CRP for at least 1 week after the diagnosis of severe acute pancreatitis, with the aim of identifying a clear peak, is considered clinically essential for controlling WON." (PMID 34386599, 2021). "One previous report indicated that the CRP level rarely reaches 300 mg/L within 3–4 days in patients with severe acute pancreatitis." (PMID 34386599, 2021). "C-reactive protein (CRP) has been reported as a predictor of the severity of acute pancreatitis (AP)." (PMID 34900460, 2021). "Although serum CRP concentration appears to be a useful biomarker to identify clinical changes in hospitalized dogs with acute pancreatitis, the decrease in serum cPLI was more consistent on a daily basis as compared to serum CRP concentration." (PMID 34250650, 2021). "The outcome parameters for evaluating the effect of corticosteroid treatment on acute pancreatitis were the clinical score (as defined by the authors), circulating CRP levels, hospitalisation duration, mortality rate and pancreas histopathology score." (PMID 34256804, 2021). "The CRP level is a prognostic factor for severe acute pancreatitis and has been identified as a predictive factor for both pancreatic necrosis and infective pancreatic cysts." (PMID 34386599, 2021). "Continuous monitoring of CRP levels during the early stage of severe acute pancreatitis is important for predicting the development of WON, especially when contrast‐enhanced CT is not available." (PMID 34386599, 2021). "In earlier human guidelines on acute pancreatitis, a CRP level > 150 mg/L was indicative of severe pancreatitis." (PMID 34256804, 2021). "High levels of NLR, RDW, glucose, and CRP at the first admission in the emergency department appear to be associated with an increased hospital stay, increased NLR, PLR, glucose, and CRP values low albumin values in acute pancreatitis." (PMID 33489590, 2020). "For example, both patient 1 and patient 7 presented with increased C-reactive protein levels because of acute pancreatitis and ectopic pregnancy surgery, respectively." (PMID 33015099, 2020). "Its expression was significantly elevated in serum from patients with acute pancreatitis along with amylase, lipase, and CRP." (PMID 32638512, 2020). "In this study, we investigated the success rates of combinations of Bedside Index of Severity in Acute Pancreatitis (BISAP) scores with C-reactive protein (CRP) values in predicting severe AP." (PMID 31114724, 2019). "The association between on admission C-reactive protein levels (CRP) and white blood cell count (WBC) and the severity and mortality of acute pancreatitis." (PMID 31551798, 2019). "The preoperative peak CRP value was increased in 153 patients with biliary pain, 163 patients admitted for acute cholecystitis, 146 with obstructive jaundice, 126 with acute pancreatitis and 41 with acute cholangitis." (PMID 31592082, 2019). "The association between C-reactive protein levels (CRP) and white blood cell count (WBC) within 24 h from the onset of pain and the severity and mortality of acute pancreatitis." (PMID 31551798, 2019). "AP, acute pancreatitis; BISAP, Bedside Index of Severity in Acute Pancreatitis; CRP, C-reactive protein; IQR, interquartile range; SD, standard deviation." (PMID 31114724, 2019). "In acute pancreatitis, only CRP level above 210 mg/L that is observed after 48 hours following the onset of the disease is regarded as a prognostic factor of SAP." (PMID 26784348, 2016).